AP1S3 (adaptor related protein complex 1 subunit sigma 3)
Description:
Subunit of clathrin-associated adaptor protein complex 1 that plays a role in protein sorting in the late-Golgi/trans-Golgi network (TGN) and/or endosomes. The AP complexes mediate both the recruitment of clathrin to membranes and the recognition of sorting signals within the cytosolic tails of transmembrane cargo molecules. Involved in TLR3 trafficking.
Synonyms: sigma1C; PSORS15
Tractability: Small molecule: a structure with a bound ligand is known. Antibody: UniProt places it where antibodies can reach, with medium confidence. PROTAC: ubiquitination databases record sites on it.
Gene: Protein-coding gene on chromosome 2 (223,667,680 to 223,838,027, reverse strand). Ensembl gene ENSG00000152056.
Subcellular location: Golgi apparatus; Cytoplasmic vesicle membrane; Membrane, clathrin- coated pit
Subcellular location (Human Protein Atlas): Vesicles
Pathways (Reactome):
Vesicle-mediated transport: Golgi Associated Vesicle Biogenesis; Lysosome Vesicle Biogenesis
Disease: Nef mediated downregulation of MHC class I complex cell surface expression
Immune System: MHC class II antigen presentation
Gene Ontology:
Molecular function: protein binding; clathrin adaptor activity
Biological process: protein targeting; melanosome assembly; platelet dense granule organization; vesicle-mediated transport; intracellular protein transport; protein transport
Cellular component: AP-1 adaptor complex; cytoplasmic vesicle membrane; cytosol; early endosome; Golgi membrane; lysosomal membrane; trans-Golgi network membrane; clathrin-coated pit; Golgi apparatus; membrane coat
Genetic constraint (gnomAD): Loss-of-function variants: 10 observed, 20.77 expected, observed/expected ratio (o/e) 0.48, 90% interval 0.3 to 0.82. The synonymous counts are far from expectation, so gnomAD's model fits this gene poorly and the ratio says little. Missense variants: 153 observed, 193.58 expected, observed/expected ratio (o/e) 0.79, 90% interval 0.69 to 0.9. Synonymous variants: 41 observed, 65.19 expected, observed/expected ratio (o/e) 0.63, 90% interval 0.49 to 0.82.
Homologues: Orthologues: macaque AP1S3 (100% identical), mouse Ap1s3 (95% identical), pig AP1S3 (95% identical), rat Ap1s3 (95% identical), chimpanzee AP1S3 (94% identical), guinea pig AP1S3 (94% identical), rabbit AP1S3 (91% identical), tropical clawed frog ap1s3 (83% identical), zebrafish ap1s3b (74% identical), Drosophila melanogaster AP-1sigma (70% identical), zebrafish ap1s3a (68% identical), Caenorhabditis elegans aps-1 (66% identical). Paralogues in human: AP1S2 (71% identical), AP1S1 (69% identical), AP2S1 (40% identical), AP3S1 (37% identical), AP3S2 (36% identical), AP4S1 (33% identical).
Diseases named in the same sentence as AP1S3 in open-access papers:
AP1S3 is named in the same sentence as 26 diseases in open-access papers, as found by Europe PMC text mining. Sharing a sentence is not in itself a finding about the gene and the disease. The quoted sentences say what the papers report.
pustular psoriasis (15 papers, 2016 to 2024). "Two genetic mutations associated with pustular psoriasis have been recently described: AP1S3 and MPO." (PMID 38448036, 2024). "Mutations in AP1S3 (σ1C) cause a severe autoinflammatory skin disorder (called pustular psoriasis) due to defects in vesicular trafficking, and AP1S3 (σ1C) is required for Toll-like receptor homeostasis." (PMID 36836259, 2023). "Except for mutations in CARD14, mutations in IL-36 receptor antagonist (IL-36RN) and adaptor-related protein complex 1 subunit sigma 3 (AP1S3) have also been identified to cause or contribute to pustular psoriasis that is a rare and severe form of psoriasis." (PMID 35075118, 2022). "Another likely pathogenic variant rs116107386 (c.11T>G: p.F4C) in the AP1S3 gene associated with pustular psoriasis has a frequency of ~ 1% in the global population." (PMID 34905135, 2021). "In this context, pustular psoriasis associated with AP1S3—including cases with GPP, acrodermatitis continua, and palmoplantar pustulosis—is recognized as an AikD." (PMID 32153585, 2020). "Recently, AP1S3 mutations were found to be associated with pustular psoriasis, and knockdown of AP1S3 resulted in the upregulation of pro-inflammatory cytokines." (PMID 29871627, 2018). "Although we previously reported that two AP1S3 mutations (p.Phe4Cys and p.Arg33Trp) account for approximately 10% of European pustular psoriasis patients, the rarity of the disease has hindered the replication of this finding." (PMID 27388993, 2016). "We therefore investigated the pathogenesis of pustular psoriasis, focusing our attention on AP1S3, a gene that is specifically mutated in this disease." (PMID 27388993, 2016). "We specifically investigated the pathogenic role of AP1S3, a gene that we found to be mutated in all forms of pustular psoriasis." (PMID 27388993, 2016). "AP1S3 mutations in pustular psoriasis reduce degradation activity in lysosomes and may favor intracellular accumulation of bacterial DNA complexes in neutrophils, leading to sustained TLR9 activation." (PMID 38448036, 2024). "AP1S1 mutations cause MEDNIK (mental retardation, enteropathy, deafness, peripheral neuropathy, ichthyosis, and keratoderma) syndrome; AP1S2 mutations are responsible for some forms of X-linked mental retardation; and AP1S3 mutations increase susceptibility to pustular psoriasis." (PMID 37108275, 2023). "However, recently, pustular psoriasis has been associated with mutations in AP1S3, CARD14, and IL356RN." (PMID 34884596, 2021). "IL36RN mutations are the genetic variant most frequently observed in patients with pustular psoriasis (5–24%), followed by AP1S3 in 7–11% and CARD14 in a very small number of subjects; the highest rates correspond to patients with GPP, and the lowest correspond to PPP in all cases." (PMID 33919434, 2021). "Pustular psoriasis may be caused by mutations in the AP1S3 gene encoding AP1S3, a protein implicated in autophagosome formation, which is elevated in keratinocytes." (PMID 31736939, 2019). "In addition, some cases with pustular psoriasis may be related to mutations in AP1S3 coding adaptor-related protein complex 1, sigma-3 subunit (AP1S3)." (PMID 32153585, 2020). "Another study investigating genetic variations in patients with pustular psoriasis found that AP1S3 mutations were in fewer GPP cases than IL36RN, and patients with AP1S3 disease alleles were mainly female." (PMID 37372477, 2023). "Loss-of-function mutations of the AP1S3 gene were found relevant in GPP, which implies pustular psoriasis as an autoinflammatory manifestation resulting from impaired vesicular trafficking." (PMID 37372477, 2023). "For GPPs, recently, genetic mutations in genes encoding IL-36RN (IL-36Ra: IL-36 receptor antagonists) and CARD14, AP1S3 (Adaptor-Related Protein Complex 1 Subunit Sigma 3) were reported in relation to pustular psoriasis development." (PMID 35330444, 2022).
pustular psoriasis (continued). "Other genes with mutations associated with pustular psoriasis include caspase-activating recruitment domain member 14 (CARD14), adaptor protein complex 1 subunit sigma 3 (AP1S3), TNFAIP3-interacting protein 1 (TNIP1), and serpin family A member 3 (SERPINA 3)." (PMID 33919434, 2021). "Taken together, these observations validate the involvement of AP1S3 in pustular psoriasis and suggest the possibility of epistasis between IL36RN and AP1S3 alleles." (PMID 27388993, 2016). "The main genes implicated in pustular psoriasis are IL36RN, CARD14, and AP1S3." (PMID 38785955, 2024). "In 2014, mutations in AP1S3, the gene encoding AP-1 complex subunit sigma 3, were found in unrelated individuals with severe pustular psoriasis, including patients with GPP not harboring IL36RN and CARD14 mutations." (PMID 34445754, 2021).
psoriasis (9 papers, 2019 to 2025). An autoimmune condition characterized by red, well-delineated plaques with silvery scales that are usually on the extensor surfaces and scalp. "In vitro studies have shown that the level of p62 is regulated by the AP1S3 protein, and mutations in the AP1S3 gene are observed in psoriasis." (PMID 36292991, 2022). "Mutations of AP1S3, such as p.Phe4Cys and p.Arg33Trp, are loss-of-function mutations and AP1S3 deficiency led to autoinflammation mediated by impaired keratinocyte autophagy and increased IL-36 signaling, finally contributing to the development of psoriasis." (PMID 35075118, 2022). "Given the various newly identified monogenic factors such as IL36RN and AP1S3 associated with significantly increased risk for psoriasis, perhaps the higher rate of consanguinity observed in the Middle East puts this population at greater risk for the development of psoriasis." (PMID 34977058, 2021). "AP1S3 mutations have been widely demonstrated as risk factors in psoriasis." (PMID 31736959, 2019). "Furthermore, individuals with psoriasis showed a particularly severe, recalcitrant phenotype that carried both the IL36RN and AP1S3 mutations." (PMID 31736959, 2019).
generalized pustular psoriasis (5 papers, 2016 to 2025). A rare and extreme form of psoriasis characterized by the appearance of sterile pustules which can take many patterns. "Other genes with mutations identified in patients with generalized pustular psoriasis include the adaptor-related protein complex 1 subunit sigma 3 (AP1S3), mutations in Myeloperoxidase (MPO) genes, Serpin Family A Member 1 (SERPINA1) and SERPINA3, TNIP1, and IL1RN." (PMID 38256115, 2024). "The most common mutation in generalized pustular psoriasis occurs in the IL-36 receptor antagonist gene, though rarer mutations include pathogenic CARD14, AP1S3, and MPO genes." (PMID 39802942, 2025). "Mutations in the adaptor-related protein complex 1 subunit sigma 3 (AP1S3) have also been found in generalized pustular psoriasis." (PMID 37628670, 2023).
breast cancer (3 papers, 2021 to 2024). A primary or metastatic malignant neoplasm involving the breast. "Previous analysis using the Cancer Genome Atlas (TCGA) demonstrated that overexpression of AP1S3 is associated with poor outcomes in breast cancer, and the staining pattern of the AP1S3 products is similar to the scattered pattern of γ1-adaptin in this study." (PMID 38265632, 2024). "miR-204 inhibits breast cancer progression by targeting multiple genes involved in tumor progression such as FOXA1, AP1S3, RIOK1, RRM2, and PRMT5." (PMID 39199587, 2024).
glioma (2 papers, 2021 to 2024). A benign or malignant brain and spinal cord tumor that arises from glial cells (astrocytes, oligodendrocytes, ependymal cells). "In addition, we conducted TCGA dataset analysis to verify whether higher expression of AP1S3 was associated with lower survival rates for glioma." (PMID 34367317, 2021). "To further determine the expression of AP1S3 in glioma, we also detected the expression of AP1S3 in glioma cells." (PMID 34367317, 2021). "As far as we know, this is the first study to show that AP1S3 acts as a biomarker for glioma and predicts the poor prognosis of glioma." (PMID 34367317, 2021). "In the following studies, our data showed that AP1S3 expression was increased in the tissues and cells of glioma." (PMID 34367317, 2021). "Collectively, our results implied that AP1S3 was a promising biomarker of glioma diagnosis and displayed as an oncogene in glioma." (PMID 34367317, 2021). "The Kaplan-Meier curve data showed that AP1S3 was closely related to the disease-free survival (DFS) of glioma." (PMID 34367317, 2021). "The link existing in the expression of AP1S3 and disease-free survival (DFS) of glioma patients was validated, so as to deeply uncover the veil of AP1S3." (PMID 34367317, 2021). "The downregulation of AP1S3 suppressed glioma cell proliferation and migration, shedding light on the possibility of AP1S3 being the biomarker and therapy target of glioma." (PMID 34367317, 2021). "AP1S3 was reported to be related to the development of many cancers, such as skin cancer and gliomas." (PMID 34367317, 2021). "The results displayed that compared with adjacent normal tissues, AP1S3 was highly expressed in 15 pairs of glioma samples." (PMID 34367317, 2021). "In our study, AP1S3 was detected to promote glioma cell proliferate by performing CCK-8 assay, and Transwell assay demonstrated AP1S3 enhanced the metastasis of glioma cell." (PMID 34367317, 2021). "Our data suggested that the expression of AP1S3 was increased in glioma in comparison with normal tissues, in line with the data of clinical samples." (PMID 34367317, 2021). "The data showed that AP1S3 was markedly increased in glioma cells, especially in SW1783 and U373, compared with normal brain cells." (PMID 34367317, 2021). "In addition, studies focusing on gene expression of AP1S3 that encodes σ1C revealed that it is highly expressed in TNBC, glioma, and pancreatic ductal adenocarcinoma (PDAC), suggesting high expression of AP-1 complex in these cancers." (PMID 38265632, 2024). "qRT-PCR was carried out to detect AP1S3 expression in glioma tissues and adjacent normal tissues." (PMID 34367317, 2021). "Nevertheless, the function of AP1S3 in glioma is not well understood." (PMID 34367317, 2021). "Here, our data revealed that AP1S3 was a glioma-specific gene." (PMID 34367317, 2021). "The function of AP1S3 is special in numerous diseases, but its exact role in glioma remains unknown." (PMID 34367317, 2021). "Our findings indicated that AP1S3 expression was increased in glioma." (PMID 34367317, 2021). "Furthermore, AP1S3-mediated promotion of glioma cell proliferation and migration was perhaps conducive to finding new biomarkers or therapy for glioma patients." (PMID 34367317, 2021). "Herein, we attempted to systematically investigate the function and mechanism of AP1S3 in glioma." (PMID 34367317, 2021). "We further explored and discussed the function of AP1S3 in glioma cells." (PMID 34367317, 2021). "Our results showed that AP1S3 had rich functions and pathways in glioma." (PMID 34367317, 2021). "What was more, our data demonstrated that the reduction of AP1S3 in glioma cells could result in the inhibition of cell proliferation, invasion, and migration." (PMID 34367317, 2021). "Besides, we attempted to evaluate the expression and function of AP1S3 in glioma." (PMID 34367317, 2021). "This and similar reports further demonstrated that the AP1S3 transcript is highly expressed in TNBC, PDAC and glioma." (PMID 38265632, 2024).
glioma (continued). "The AP1S3 gene expression map (49 LGG and 81 GBM) of 130 glioma patients was downloaded from GSE4271." (PMID 34367317, 2021). "We proved that AP1S3 might be useful to diagnose GBM and was reported to be related to DFS of glioma patients." (PMID 34367317, 2021). "Additionally, the AP1S3 level was dramatically upregulated in glioblastoma (GBM) samples, but greatly reduced in low-grade glioma (LGG) samples when compared to that in normal tissues." (PMID 34367317, 2021).
palmoplantar pustulosis (2 papers, 2022 to 2023). A rare skin disease characterized by chronic eruption of sterile pustules on an erythematous and desquamative background, affecting the palms and soles, sometimes also the lateral aspects of hands and feet. "Lastly, AP1S3 variants seem most closely associated with palmoplantar pustulosis." (PMID 38103162, 2023). "It seems that AP1S3 deficiency is the most closely associated with palmoplantar pustulosis." (PMID 38103162, 2023).
colon cancer (1 paper, 2024). "In colon cancer, adaptor related protein complex 1 subunit mu 1 (AP1M1), subunit sigma 2 (AP1S2), and subunit sigma 3 (AP1S3) are common overregulated genes and might be related to the accumulation of IFITM3 protein on the cell surface." (PMID 39228892, 2024).
lung carcinoma (1 paper, 2026). "Overall, these converging multi-omics findings highlight AP1AR and AP1S3 as the most clinically relevant AP-1 adaptors in lung cancer, elucidating their roles in proliferation, stress adaptation, immune modulation, and drug response." (PMID 41438582, 2026). "A systematic multi-omics analysis was conducted for the eight AP-1 adaptor complex genes (AP1AR, AP1B1, AP1G1, AP1G2, AP1M1, AP1M2, AP1S1, and AP1S3) to characterize their roles in lung cancer." (PMID 41438582, 2026). "Our analyses identified AP1S3 as a second clinically relevant AP-1 adaptor gene in lung cancer." (PMID 41438582, 2026).
pancreatic ductal adenocarcinoma (1 paper, 2021). An infiltrating adenocarcinoma that arises from the epithelial cells of the pancreas. "Another study demonstrated that highly expressed AP1S3 was involved in the pathogenesis of pancreatic ductal adenocarcinoma and a significant predictor of a poor prognosis of PDAC." (PMID 34367317, 2021).
cancer (4 papers, 2020 to 2021). A tumor composed of atypical neoplastic, often pleomorphic cells that invade other tissues. "Finally, similarly to that of AP1S2, the upregulation of AP1S3 was found to be linked with cancer cell aggressiveness among breast cancer patients and could be a target for small RNA silencing, which highlights its potential as a target for cancer treatment." (PMID 34565296, 2021). "Up to date, there are few reports on the role of AP1S3 in human cancers." (PMID 34367317, 2021). "Thus, they function as cancer-promoting genes, such as FOXQ1, PHLDA2, LPCAT2, AP1S3, and EPS8." (PMID 32977589, 2020).
tumor (2 papers, 2021 to 2026). "Integration with clinical annotations showed higher AP1AR and AP1S3 expression in advanced-stage tumors and smoker-associated samples compared to non-tumor tissues, suggesting a link to aggressive disease phenotypes." (PMID 41438582, 2026). "Pathological stage-specific analyses revealed progressive upregulation of AP1AR and AP1S3 with advancing tumor stage, whereas AP1S1 expression remained relatively stable." (PMID 41438582, 2026). "Among them, DPY30, EREG, PLA2G16, ZNF185, PADI1, INPP4B and AP1S3 have been reported to be involved in tumor genesis and progression, and they were significantly positively correlated with risk score." (PMID 34090418, 2021).
AP1S3 also shares sentences with these, for which no sentence is quoted: arrhythmogenic right ventricular cardiomyopathy (1 paper); autoimmune thyroid disease (1); deafness (1); enteropathy (1); glioblastoma (1); ichthyosis (1); liver cancer (1); mental retardation (1); peripheral neuropathy (1); plaque psoriasis (1); psoriasis 2 (1); Salmonella Infections (1); schizophrenia (1); skin cancer (1); skin disorder (1).